MSN (moesin)
Diseases named in the same sentence as MSN in open-access papers (continued):
Sharing a sentence is not in itself a finding about the gene and the disease.
tumor (continued). "Moesin, as its component, has also been found to play an important role in the prognosis of cancer patients, tumor metastasis, drug resistance, and others." (PMID 33838692, 2021). "But it should be pointed out that moesin has been found to have unique roles in other tumor-related processes except regulating immunity." (PMID 33838692, 2021). "For example, Moesin (MSN) activates tumor progression by interacting with CD44 to induce Wnt/b-catenin pathway proliferation." (PMID 34512630, 2021). "The expression of moesin in PC tissues has close relations with the pathological stage of the disease, nerve infiltration, tumour location, and pain severity." (PMID 33573274, 2021). "Downregulation of lncRNA XIST activated epithelial-mesenchymal transition, MSN/c-Met, and release of exosomal miR-503, accelerated primary tumor growth as well as metastasis in the brain." (PMID 34707990, 2021). "In summary, these research results showed that moesin is an indicator that worth exploring in tumors, and in-depth study will be also beneficial for the tumor clinical diagnosis and treatment." (PMID 33838692, 2021). "Higher levels of expression of mesenchymal-associated genes SNAI1, SERPINE1, MSN, NRP1 and LAMC2 were observed in CTCs compared to primary tumour in three of the four models (the exception being LuCaP96)." (PMID 34206049, 2021). "SYNDECAN-1, CD44, and MOESIN all have roles in cytoskeleton (such as the actin family of proteins) regulation, cell adhesion and migration and tumor tissue remodeling." (PMID 34867197, 2021). "Among them, Moesin is particularly attractive for its curial role in organizing membrane domains and receptor signaling, as well as regulating the metastasis of tumor cells." (PMID 33292278, 2020). "Expression of moesin correlated with tumor size, metastasis, differentiation, and lymphocytic infiltration in OSCC patients." (PMID 33171868, 2020). "To further clarify that CD44 cross-linking indeed regulates tumor cell migration and invasion by affecting p-Moesin in BrCas, we reduced Moesin expression in MDA-MB-231 and BT-549 by RNA interference." (PMID 33292278, 2020). "Downregulation of XIST activated EMT and stimulated c-Met through stabilizing MSN-mediated protein, which contributed to the activation of tumor cells' stemness." (PMID 31214490, 2019). "Podoplanin has been reported to enhance tumour invasion by enhancing cell motility through interaction with actin in the cytoskeleton via proteins such as ezrin, radixin, and moesin." (PMID 31452946, 2019). "Decreased expression of XIST stimulated EMT and activated c-Met via MSN-mediated protein stabilization, which resulted in the promotion of stemness in the tumor cells." (PMID 31214490, 2019). "The study on brain metastasis of BC found that the lncRNA XIST suppressed EMT and the MSN/c-Met axis via MSN-mediated protein stabilization, which leads to the attenuation of stemness in the tumor cells." (PMID 31744046, 2019). "Moesin promoted tumour cell invasion in that in vitro 3D cell migration assays revealed that moesin depleted-cells exhibited reduced invasiveness." (PMID 26983550, 2016). "While the expression levels of Rho A, ROCK2 and moesin were positively correlated with Tumor differentiation, and TNM stage." (PMID 26846339, 2016). "This identified Slug and Moesin expression in aneuploid cells that were also more frequent at the migratory edge than in the tumor core." (PMID 27140846, 2016). "Expression of moesin has been correlated with increased tumour size and invasive capability, and there was an aberrant trafficking of the protein from plasma membrane to the cytosol in oral squamous carcinoma cell (OSCC) in which moesin was knocked down." (PMID 26983550, 2016). "The 4.1 proteins family is characterized by FERM (Four-point-one, Ezrin, Radixin, Moesin) domains, many of which have related functions in influencing the biologic characteristics of tumor cells, as reported mainly with regard to cancer progression." (PMID 27487132, 2016).
tumor (continued). "A final visual evidence for cytoskeletal remodeling was provided by immunofluorescence profiling of F-actin and moesin expression in sorted euploid and aneuploid tumor cells subjected to scratch/wound healing assays." (PMID 27140846, 2016). "Positive expression of phosphorylation of moesin was all correlated positively with tumor differentiation, TNM stage and dissemination in liver and portal vein invasion." (PMID 26846339, 2016). "The significance of moesin immunoreactivity in tumour tissues, however, still remains to be established." (PMID 23420497, 2013). "We show that the significant role of CD44-moesin interaction in cellular migration is in response to hyaluronan, an important component of the tumor microenvironment." (PMID 23855374, 2013). "The NEP N-terminus also affects tumor formation by competing with the hyaluronan receptor CD44 for Ezrin/Radixin/Moesin (ERM) binding thereby reducing the invasive capacity of cancer cells." (PMID 20957047, 2010). "Collectively, these results suggest that MSN promotes tumor growth and metastasis in TNBC." (PMID 40696387, 2025). "In addition, ADRr tumor cells showed more formation of p-STAT3/MSN complex that translocated to the nucleus compared to the TNBC cell lines without ADR resistance and the complex was enhanced by IL-6 stimulation." (PMID 40696387, 2025). "Interestingly, upon MSN upregulation in tumor cells, there was an increase in phosphorylated NF-κB (p-NF-κB) under IL-6 treatment." (PMID 40696387, 2025). "As MSN contains a FERM domain identically found in JAK2 and IL-6 stimulates hyperactivation of JAK signaling, we next examined whether IL-6 acts on tumor cells to activate MSN." (PMID 40696387, 2025). "Additionally, MSN expression significantly enhanced cell migration and invasion abilities of tumor cells." (PMID 40696387, 2025). "High expression of PADI2 and PADI3 can reduce the expression of moesin, increase extracellular vesicles (EVs) to release tumor-promoting factors, reduce EV tumor suppressors, and increase the invasiveness of tumor cells, thereby promoting the malignant progression of PDAC." (PMID 37020554, 2023). "Building upon our preceding investigations, wherein several tumor-suppressive proteins, including Moesin and Enolase 1, were enriched in tumor-suppressive CM, prompting the conversion of both tumor and non-tumor cells into iTSCs, we turned our focus to the role of ALDOA." (PMID 37896207, 2023). "We identified tumor suppressor FBXW2 as the first bonafide E3 ligase for Moesin." (PMID 37736741, 2023). "Besides osteoblast-derived CM, EO771 tumor cell-derived CM by the overexpression of Lrp5, MSN, or OPN reduced the MTT-based viability of EO771 parent cells." (PMID 34976221, 2022). "The secretome was enriched with atypical tumor suppressors such as Hsp90ab1 and moesin (MSN)." (PMID 34976221, 2022). "Activation of WNT signaling in osteoclasts, osteoblasts, and cancer cells resulted in their conversion to tumor-suppressive cells with secretomes enriched with Hsp90ab1, enolase 1 (Eno1), moesin (MSN), and ubiquitin C (Ubc), which acted as atypical tumor-suppressors." (PMID 35994202, 2022). "Ezrin expression was statistically significantly lower in the CGTH (p < 0.01) and FTC-133 (p < 0.05) cells than in NTHY cells, whereas Moesin expression was significantly higher in all tumor cell lines tested (p < 0.05 for FTC-133 and p < 0.01 for CGTH, 8505c, TPC-1 BcPAP)." (PMID 35328683, 2022). "And it is worth noting that moesin promotes the infiltration of TCM cells, which may indicate that moesin can indeed maintain the body’s own immunity against tumor cells for a long time to improve the prognosis of cancer patients." (PMID 33838692, 2021).
tumor (continued). "Previous reports have shown some evidence that relate moesin with MT1-MMP expression levels in tumour cells, however, the molecular mechanisms involved are unknown." (PMID 32028690, 2020). "Furthermore, clinically relevant genes that are associated with tumor growth such as VIM, ITGB1, FOXQ1, FN1, MSN, CXCL and TMPRSS4 were also downregulated." (PMID 32784836, 2020). "Taken together, these results suggested that CD44 cross-linking may regulate tumor cell migration and invasion by altering the phosphorylation of Moesin." (PMID 33292278, 2020). "One MECA de novo tumor harbored a fusion between exon 9 of moesin (MSN) and exon 20 of ALK." (PMID 29084941, 2017). "Interestingly, microscopic analyses also revealed ezrin and moesin expression in the stromal compartment of the BC tumour specimens and in its blood vessels." (PMID 23420497, 2013). "Interestingly, they also observed moesin expression in the stromal compartment and tumour blood vessels, but the significance of this expression was not investigated in detail." (PMID 23420497, 2013). "EMR proteins share 75% sequence identity and thus it is logical to hypothesize that like ezrin, radixin and moesin might be involved in tumor cell migration." (PMID 22272721, 2012). "It suggested that moesin may play a role in LAM by influencing the tumor microenvironment." (PMID 38267973, 2024). "Also, this study focused on the target proteins from cell-surface and secreted proteins, but other cytoplasmic or nuclear proteins, such as ENO1 and MSN, may act as extracellular tumor-suppressing proteins." (PMID 37894284, 2023). "Analysis of ezrin and moesin protein expression and patient clinicopathological parameters revealed significant correlations between protein expression and the presence of lymph node metastases in the tumour compartments (P = 0.047 and P = 0.038, respectively)." (PMID 23420497, 2013). "Whole-genome proteomics analysis revealed that Moesin (MSN), which acted as an oncogene in tumor cells, was enriched in CM as an extracellular tumor-suppressing protein." (PMID 41750310, 2026). "Given MSN's role in chemoradiotherapy resistance, we explored its effects on GSC‐driven tumor progression both in vitro and in vivo." (PMID 39921260, 2025). "Together, these findings highlight that MSN is indispensable for GSC proliferation and maintenance of stemness, both in vitro and in vivo, driving tumor growth in GBM." (PMID 39921260, 2025). "Mechanistic insight shows that Moesin prevents FBXW2-SKP2 interaction and attenuates FBXW2-mediated SKP2 polyubiquitination and degradation ultimately leading to tumor growth." (PMID 37736741, 2023). "In the TCGA database, five transcripts for the selected tumor-suppressing proteins (CALR, ENO1, HSP, MSN, and UBC) were significantly upregulated in OS cells." (PMID 36943734, 2023). "As an alternative option, the combination of multiple tumor-suppressing proteins such as PABPC1, ENO1, MSN, etc. can be considered a protein-based cocktail therapy." (PMID 36923539, 2023). "Among them, the actions of 6 tumor-suppressing proteins, ENO1, Ubiquitin C (UBC), Moesin (MSN), heat shock protein 90ab1 (HSP90ab1, aka HSP90β), Calreticulin (CALR), and Histone H4 (H4), have been documented with a proposed mechanism 12-14." (PMID 37056934, 2023). "Both MSN and CD44 function in a context-dependent fashion, and their interactions in the extracellular domain are considered necessary for their anti-tumor action." (PMID 37056934, 2023). "The anti-tumor action of ENO1 and MSN was mediated at least in part by Mtdh, a prognostic marker that substantially reduces the survival rate of cancer patients." (PMID 36923539, 2023). "The results indicated that ENO1, MSN, and PABPC1 were double-edged swords, acting as intracellular tumor promoters and extracellular tumor suppressors." (PMID 36923539, 2023).
tumor (continued). "Previous studies for iTSCs showed that MSC CM, generated by the activation of Wnt and PI3K signaling pathways, were enriched with extracellular tumor-suppressing proteins such as CALR, ENO1, HSP, MSN, and UBC." (PMID 36943734, 2023). "Through comprehensive mass spectrometry-based proteomics analyses of iTSC-derived CM, it became evident that the enriched pool of tumor-suppressing proteins encompassed entities such as Enolase 1 (ENO1), Moesin (MSN), and Heat shock protein 90 (HSP90AB1)." (PMID 37894284, 2023). "There is a study on the correlation between MSN and MMP9 showed that, in individual tumours, the expression of MSN and MMP9 remains consistent, which jointly promotes tumour metastasis." (PMID 35557941, 2022). "MiR‐200b is another key tumor‐suppressive miRNA that inhibits tumor metastasis through regulating various proteins, such as ZEB and moesin." (PMID 35441157, 2022). "Patients overexpressing ANXA5, FKBP10, MSN, and PYGL in the tumor tissues had significantly shorter OS compared to the low expressed group in IS1–IS3 subtypes." (PMID 34512630, 2021). "Besides, recent studies have shown that moesin may also play a role in tumor drug resistance." (PMID 33838692, 2021). "Interestingly, compared with changing the migration and invasion ability of a single cancer cell, studies have pointed out that Rab11 may trigger the collective migration of tumor cells by controlling the activity of moesin, but the more specific mechanisms still need further explored." (PMID 33838692, 2021). "Moesin is a member of the ERM (ezrin, radixin and moesin) proteins that participate in cell migration and tumor invasion through transductional signals sent to actin filaments by glycoproteins, such as podoplanin." (PMID 29310601, 2018). "Moesin translocation from plasma membrane to the cytoplasm of neoplastic cells has been demonstrated in a previous study and it may reduce the ability to form cell-cell contacts, as well as, influence the cytoskeleton remodeling and tumor invasion process, when overexpressed in the cytoplasm." (PMID 29310601, 2018). "Moesin (MSN), a member of the ezrin-rdixin-moesin family and Claudin7 (CLDN7), a tight junction protein, both play a role in tumor cell metastasis." (PMID 22272721, 2012). "One group was associated with rapid proliferation, oxidative phosphorylation, invasiveness, and tumor size (MRPS23, MRPL11, CKS2, LSM3, TBX3, MSN) and another with hypoxia tolerance, anaerobic metabolism, and high lactate content (PDK2, KLF3)." (PMID 17054779, 2006). "All proteins were expressed in tumor cells, and expression was also seen in stroma cells for HK2, MEF2A, and MSN." (PMID 17054779, 2006). "In addition, miR-133a-3p targeted Moesin (MSN), which inhibited the anti-tumor effects of APS by maintaining the stability of PD-L1." (PMID 38155974, 2023). "Besides ENO1 and MSN, the engineered CM was enriched with polyadenylate-binding protein 1 (PABPC1) which also showed an opposing tumor-regulating role inside and outside tumor cells." (PMID 36923539, 2023). "Together with the tumor-suppressing proteins such as CALR, ENO1, HSP, MSN, and UBC, which were enriched in tumor-suppressive CM, six recombinant proteins, such as HISTONE H4, PPIB, GJA1, CPE, S100A11, and PCOLCE, were identified as extracellular tumor-suppressing proteins." (PMID 36943734, 2023). "tRF-19-R118LOJX might play a crucial role in angiogenesis, tumor cell migration, invasion, and proliferation, and survival through the target genes COLA1, FN1, and MSN." (PMID 37864150, 2023). "Further investigation of the regulatory mechanism may provide better insight into the precise roles of Hsp90ab1, MSN, CD44, and FN1 in the anti-tumor action of Lrp5 CM." (PMID 34976221, 2022). "It was suggested that impaired interaction between β-catenin and moesin, E-cadherin, or ZYX could impair the formation of cell adhesion junctions/adherens junctions and thus promote tumor progression." (PMID 35740950, 2022).
tumor (continued). "MSN knockdown resulted in reduced in vivo peritoneal metastasis formation, whereas this did not affect in vitro outgrowth or subcutaneous tumor growth rate in vivo." (PMID 35927254, 2022). "The result showed that the inhibitory effect of Lrp5 CM, Hsp90ab1, and MSN was largely selective to tumor cells than non-tumor cells." (PMID 34976221, 2022). "Moreover, a well-described tumor suppressor miR-200c targets TUBB3, MSN, and ARHGAP19, which regulate multiple cytoskeletal-related events." (PMID 34298609, 2021). "Downregulation of lncRNA XIST activated three distinct pathways, epithelial-mesenchymal transition (EMT), MSN/c-Met, and release of exosomal miR-503, thus knockout of XIST in mice mammary glands promoted the primary tumor growth as well as metastasis in the brain." (PMID 34707990, 2021). "Although, moesin and ezrin had been proposed to function as oncogenes in various tumor cell lines, their potential roles in RCC is not known." (PMID 34503512, 2021). "The muscle invasive tumour, however, showed a basal subtype (higher expression of CDH3, CD44, KRT5 and KRT6A) and likewise high aggressiveness (higher expression of KPNA2, BIRC5, CDC25B, COL4A1, and MSN)." (PMID 28916750, 2017). "Based on this point, we have sequentially identified tumor suppressive miRNAs and miRNA-mediated molecular targets contributing to cancer cell invasion and metastasis, such as miR-1 regulates TAGLN2, miR-145-FSCN1/LASP1, miR-133a-MSN and miR-138-VIM." (PMID 23159910, 2012). "In addition to a number of reported mRNA transcripts, such as ILEI, EGFR, MOESIN, FAM3C, JAK2 and EIF5A2, we identified ZEB2, an EMT‐related transcription factor that is vital for tumor metastasis, as a potential transcript regulated by PCBP1 at the translational level." (PMID 41117067, 2025). "IFNGR2, KLF10, PLAUR, MSN, and IKBIP, whose coefficients of risk score were >0, had positive correlations with risk score, stromal score, immune score, and ESTIMATE score and negative relationships with tumor purity." (PMID 38137116, 2023). "Besides CD44, the tumor-suppressive action of extracellular ENO1 and MSN was mediated by Mtdh." (PMID 36923539, 2023). "Thus, ANXA5, FKBP10, MSN, and PYGL might be presented by APCs to the T cells and recognized by the B cells to induce a tumor response." (PMID 34512630, 2021). "Especially in regulating the immunity, but most results came from direct studies on immune cells, there is no clear conclusion on whether moesin has similar effects in tumor cells." (PMID 33838692, 2021). "For the specific mechanism of high expressed moesin to improve the prognosis of LUAD patients, in view of the fact that moesin has been found to regulate the body's own immunity in immune cells, we thought it may also have a similar effect in tumor cells." (PMID 33838692, 2021). "Furthermore, six tumor progression genes (GNAI2, ODC1, APP, TNFRSF12A, BASP1, and LARP6) and nine migration and metastasis‐related genes (MSN, FLOT1, LAMB3, MYL9, ITGB1, FTH1, TPM4, and PMEPA1), which could explain the invasive characteristics of SCC, were identified." (PMID 40776410, 2025). "Moreover, the expression levels of MYL9 and TPM2, but not MSN were significantly associated with the advanced TNM stage, implying that MYL9 and TPM2 may play a key role in tumor progression, and predicted a worse outcome in CRC." (PMID 37031206, 2023). "Another importance is that gene silencing of ezrin, but not of radixin and moesin significantly decreased the cell surface expression of P-gp without affecting the levels of the ABCB1 mRNA in LS180 cells cultured at the acidic pH condition which mimics the actual tumor microenvironment." (PMID 33974673, 2021). "For instance, the expression level of CD44, which may interact with Eno1 and MSN, can be expressed higher in cancer cells than noncancer cells, and thus the impact of CD44-mediated cytotoxicity is stronger in tumor cells." (PMID 36810561, 2023).